Y_RNA (Y RNA )
Gene: Miscellaneous RNA gene on chromosome 17 (7,537,096 to 7,537,196, reverse strand). Ensembl gene ENSG00000201489.
Homologues: Orthologues: chimpanzee Y_RNA (97% identical), macaque Y_RNA (94% identical). Paralogues in human: Y_RNA (95% identical), Y_RNA (94% identical), Y_RNA (93% identical), RNY3 (92% identical), RNY3P1 (92% identical), Y_RNA (92% identical), Y_RNA (91% identical), Y_RNA (90% identical), Y_RNA (89% identical), RNY3P5 (88% identical), Y_RNA (88% identical), RNY3P10 (87% identical), and 100 more.